C1S (complement C1s)
Diseases named in the same sentence as C1S in open-access papers (continued):
Sharing a sentence is not in itself a finding about the gene and the disease.
lupus nephritis (4 papers, 2022 to 2023). Glomerulonephritis in the context of systemic lupus erythematosus. "However, the positive rate of anti-C1s auto-antibody was markedly lower (6.9%) in a study of a larger group of patients with lupus nephritis, and the presence of anti-C1s and anti-C1r auto-antibodies did not correlate with the clinical parameters of the disease." (PMID 36275687, 2022).
rheumatoid arthritis (4 papers, 2014 to 2024). A chronic, systemic autoimmune disorder characterized by inflammation in the synovial membranes and articular surfaces. "Although it is a multifactorial disease, there is an overwhelming clinical evidence showing that homozygous deficiency in any of the classical pathway proteins – C1q, C1r, C1s, C4, and C2 – predisposes an individual to develop SLE and other autoimmune diseases such as rheumatoid arthritis (RA)." (PMID 25018754, 2014).
Alzheimer disease (3 papers, 2016 to 2025). A progressive, neurodegenerative disease characterized by loss of function and death of nerve cells in several areas of the brain leading to loss of cognitive function such as memory and language. "The C1s gene was a significant hit in a recent GWAS of Alzheimer’s disease, and reduced levels of C1s have been observed in the cerebrospinal fluid of Alzheimer’s disease patients." (PMID 39951190, 2025). "Finally, we successfully verified significantly lower levels (p<0.05) of eight proteins (A2GL, APOM, C1QB, C1QC, C1S, FBLN3, PTPRZ, and SEZ6) in Alzheimer’s disease compared to controls using an antibody-based detection method." (PMID 26950848, 2016).
cutaneous squamous cell carcinoma (3 papers, 2022 to 2024). "C1S was also observed to promote tumor growth and survival in renal cancer and cutaneous squamous cell carcinoma." (PMID 35493104, 2022). "The growth of cutaneous squamous cell carcinoma and non-small-cell lung cancer was promoted by tumor-cell-derived complement components C1r and C1s." (PMID 35726234, 2022).
glaucoma (3 papers, 2017 to 2021). Increased pressure in the eyeball due to obstruction of the outflow of aqueous humor. "We quantified the majority of key proteins associated with classical complement pathway, such as C1q, C1s, C1r, C4a, C4b, C3, C5, C6, C7, C8a, C8b, C8g and C9, as up-regulated in glaucoma condition for both vitreous and retinal tissues when compared to the controls." (PMID 28978942, 2017). "Earlier studies have shown that immune-related proteins and several members of the complement components including C1S, C1r, C7-C9, and CFH are activated in glaucoma." (PMID 33808966, 2021).
glioma (3 papers, 2020 to 2021). A benign or malignant brain and spinal cord tumor that arises from glial cells (astrocytes, oligodendrocytes, ependymal cells). "We identified C1S as a new potential biomarker in glioma tissue based on its prognostic and OS-predictive value and predicted that C1S plays a crucial role in the ceRNA network." (PMID 33579282, 2021). "Furthermore, C1RL probably plays an immunosuppressive role in the pathogenesis of glioma by triggering the activation of haptoglobin and C1s." (PMID 32993564, 2020). "C1RL may trigger the classical complement pathway by activating C1s and thus contribute to the pathogenesis of glioma." (PMID 32993564, 2020). "C1S, as a protease involved in the classical complement pathway, was recently reported to be associated with tumor immunity and the promotion of tumor growth; however, it has not been studied as an oncogene in gliomas." (PMID 33579282, 2021).
melanoma (3 papers, 2016 to 2023). A malignant, usually aggressive tumor composed of atypical, neoplastic melanocytes. "Therefore, we investigated the expression of complement components C1R, C1S, C5, and C3 by qRT-PCR in MCs treated with melanoma cell-derived conditioned medium." (PMID 35669782, 2022). "We initially searched for the presence of C1q, C1s, C4 and C3 in a panel of 30 invasive malignant neoplasm specimens including 6 cases of colon adenocarcinoma, 6 cases of melanoma, 6 cases of lung adenocarcinoma, 6 cases of breast adenocarcinoma and 6 cases of pancreatic adenocarcinoma." (PMID 26831747, 2016). "Similar to the mouse melanoma model data, the S1 population (PDGFRAhi PDPNhi CD34hi) was characterized by the expression of genes involved in the regulation of immune cell recruitment (cytokines: CXCL12; complement factors: CFD, C3, C1S, CFH)." (PMID 36929873, 2023).
Obesity (3 papers, 2019 to 2023). Accumulation of substantial excess body fat. "It is known that C1q binding to antigen–antibody immune complexes will activate C1s and the C1 complex, and that C1q can activate the WNT signalling pathway that is known to play a role in obesity." (PMID 37886940, 2023).
paroxysmal nocturnal hemoglobinuria (3 papers, 2022 to 2025). Paroxysmal nocturnal hemoglobinuria (PNH) is an acquired clonal hematopoietic stem cell disorder characterized by corpuscular hemolytic anemia, bone marrow failure and frequent thrombotic events. "The inhibition of activated complement has already demonstrated notable success in clinical practice, for example, C3 and/or C5 inhibitors for paroxysmal nocturnal hemoglobinuria (PNH) or targeting C1s in cold agglutination disease." (PMID 36291163, 2022).
periodontitis (3 papers, 2016 to 2019). An acute or chronic inflammatory process that affects the tissues that surround and support the teeth. "No mutations in C1R or C1S were detected in 71 individuals with aggressive periodontitis, which is a main differential diagnosis to pEDS." (PMID 27745832, 2016).
preeclampsia (3 papers, 2022 to 2024). Preeclampsia is a hypertensive disorder of pregnancy that is characterized by new-onset hypertension with proteinuria presenting after 20 weeks of gestation, and depending on mild or severe forms may initially present with severe headache, visual disturbances, and hyperreflexia. "Complement C1s protein is elevated in maternal plasma of the women with preeclampsia, and is implicated in the remodeling process of the spiral arteries before the manifestation of clinical disease." (PMID 35069847, 2022). "Blood samples were taken from all patients with preeclampsia to measure signal peptide complement C1r/C1s, Uegf, and Bmp1, and epidermal growth factor-containing protein 1 levels at the time of hospitalization." (PMID 38451587, 2024). "In multivariate analysis, signal peptide complement C1r/C1s, Uegf, and Bmp1, and epidermal growth factor-containing protein 1 was determined as an independent predictor for preeclampsia (OR: 1.678, 95%CI 1.424-1.979, p<0.001)." (PMID 38451587, 2024).
atherosclerosis (2 papers, 2020 to 2025). A disease characterized by the build-up of fatty material and calcium deposition in the arterial wall resulting in partial or complete occlusion of the arterial lumen. "Additionally, complement activation contributes to vascular damage in atherosclerosis, and C1S may be involved in promoting inflammation and SMC dysfunction in atherosclerotic lesions." (PMID 41301179, 2025).
clear cell renal cell carcinoma (2 papers, 2022). "In clear cell renal cell carcinoma, local production and activation of C1s drove tumor progression and was associated with poor prognosis." (PMID 36275687, 2022). "It has also been found that macrophage produced C1q and tumor cell-derived C1r, C1s were assembled in clear cell renal cell carcinoma and resulted in an immunosuppressive microenvironment that promotes tumor progress." (PMID 36275687, 2022).
Dengue (2 papers, 2014 to 2019). "Therefore, with the decreased expression of C1S in our study, the activation of complement system is reduced, suppressing severe dengue pathogenesis and allowing only subclinical symptoms to be manifested." (PMID 24727912, 2014).
endometriosis (2 papers, 2023 to 2025). The growth of functional endometrial tissue in anatomic sites outside the uterine body. "Multi-omics analysis has revealed that up-regulated expression of complement (C1S, C1QA, C1R and C3) was positively correlated with tissue factor in endometriosis." (PMID 38012607, 2023).
ischemic stroke (2 papers, 2020 to 2024). A stroke disorder caused by obstruction of blood flow to the brain, due to thrombotic (local blood clot formation) or embolic (due to a blood clot or other material traveling from another site) event. "We observed that C1s assists in the activation of C3 and was upregulated in ischemic stroke patients." (PMID 32466277, 2020). "Taken together, C1s may be highly expressed in ischemic stroke patients to activate the complement system following ischemic stroke, which would act to restore brain injury by promoting C3 activation." (PMID 32466277, 2020).
renal cell carcinoma (2 papers, 2021 to 2024). "C1q mediated recruitment of TAM: In renal cell carcinoma, tumor cells were shown to produce high levels of C1r, C1s, C4, and C3." (PMID 34572075, 2021).
staphylococcus aureus infection (2 papers, 2023). An infectious process in which the bacteria Staphylococcus aureus is present. "The genes C1QA, C1QB, C1QC, C1S, C3, and C4A in cluster 2 were predominantly enriched in top ten pathways including Staphylococcus aureus infection, pertussis and complement and coagulation cascades." (PMID 37409113, 2023). "It seems that the importance of the classical complement pathway (along with the alternative pathway) depends on the C1s-driven immune response to the Staphylococcus aureus infection and the role of Staphylococcus aureus toxins in ocular damage and inflammation." (PMID 38004422, 2023).
Achalasia (1 paper, 2023). A disorder of esophageal motility characterized by the inability of the lower esophageal sphincter to relax during swallowing and by inadequate or lacking peristalsis in the lower half of the body of the esophagus. "In the current study, complement C1q, C1s, C2, C3, C4-A, C4-B, C5, C6, and C9 were all upregulated in the achalasia group." (PMID 37324545, 2023).
actinic keratosis (1 paper, 2024). A precancerous lesion of the skin composed of atypical keratinocytes. "Serine proteases, C1r, and C1s, were found to be significantly overexpressed in RDEB-associated and invasive sporadic cSCCs, relative to cSCC in situ, actinic keratosis, and normal skin." (PMID 38769503, 2024).
age-related macular degeneration (1 paper, 2022). Age-related loss of vision in the central portion of the retina (macula), secondary to retinal degeneration. "It has been shown recently that the expression of C1s and another two other genes is associated with Age-related macular degeneration (AMD), a progressive neurodegenerative disease of the central retina and a leading cause of vision loss in older adults worldwide." (PMID 36275687, 2022).
anemia (1 paper, 2025). A reduction in the number of red blood cells, the amount of hemoglobin, and/or the volume of packed red blood cells. "Sutimlimab, a monoclonal antibody targeting C1s, improves anemia by selectively inhibiting the upstream processes of the classical complement pathway." (PMID 40741579, 2025).
aneurysm (1 paper, 2022). Bulging or ballooning in an area of an artery secondary to arterial wall weakening. "Human aortic samples were collected from MFS and non-MFS aneurysm patients to study complement factor gene expression C1R, C1S, C3AR1, and C5AR1 and SMC gene ACTA2." (PMID 36279189, 2022). "Of the complement factor genes examined, only C1S was clearly expressed in MFS, at lower levels when compared to the non-MFS aneurysm samples." (PMID 36279189, 2022).
arrhythmogenic right ventricular cardiomyopathy (1 paper, 2016). "Besides, some other ones were correlated with arrhythmogenic right ventricular cardiomyopathy (e.g. ACTN4, CTNNA1 and ITGB5), as well as complement and coagulation cascades (e.g. C1R and C1S)." (PMID 27613243, 2016).
Arthritis (1 paper, 2023). Inflammation of a joint. "In dogs with arthritis, active forms of C1r and C1s, along with reduced concentrations of IGFBP-5, IGFBP-3 and IGF-1, were present in their synovial fluid." (PMID 38002958, 2023).
autoimmune hepatitis (1 paper, 2022). Hepatitis caused by autoantibodies. "SLE patient with C1s mutations has been reported with discoid rash, generalized seizure, autoimmune thyroiditis, autoimmune hepatitis and diffuse proliferative glomerulonephritis with full house deposition of glomerular immunofluorescence in their kidney biopsy consistent with LN." (PMID 35964089, 2022).
breast tumors (1 paper, 2019). "We found that signal peptide-CUB (complement protein C1r/C1s, Uegf, and Bmp1)-EGF (epidermal growth factor) domain-containing protein 2 (SCUBE2), a tumor suppressor gene, was hypermethylated in breast tumors." (PMID 31404982, 2019).
cardiomyopathy (1 paper, 2016). A disease of the heart muscle or myocardium proper. "Some DEGs related to cytoskeleton organization (e.g. MTSS1, ACTN4 and CALD1), cardiomyopathy (e.g. ITGB5) and immune response (e.g. C1S and C1R), as well as some regulators (e.g. LEF1 and hsa-miR-33a) might play pivotal roles in the progression of DN." (PMID 27613243, 2016).
chronic hepatitis C (1 paper, 2022). "To verify the results of the trial study, we examined the levels of the 9 proteins, IGHV, GAPDH, C1s, GRP78, V-ATPase, PPBP, CD9, Lp(a) and SAP, in EVs isolated from the sera of another 80 patients with chronic hepatitis C before DAA treatment." (PMID 35797333, 2022).
chronic inflammatory demyelinating polyneuropathy (1 paper, 2025). "In 2023, Sanofi SA’s sutimlimab (SAR-445088; formerly BIVV-020), a humanised anti-C1s monoclonal antibody, was approved for conducting clinical trials for chronic inflammatory demyelinating polyneuropathy (CIDP), a rare neuromuscular disease, using efficacy data generated using an organ chip model." (PMID 39931243, 2025).
complement deficiency (1 paper, 2016). A genetic deficiency of any of the component of the complement system (including the classical, alternative, and terminal pathway components), that can either be acquired or inherited. "Deficiencies in subcomponents C1r and C1s were among the earliest reports linking complement deficiency with human glomerulonephritis or a lupus-like disease." (PMID 26913032, 2016). "In the following sections, we will describe genetic complement deficiency states associated with SLE for each component of the early CP (C1q, C1r, C1s, C4, and C2)." (PMID 26913032, 2016).
diabetic kidney disease (1 paper, 2025). Progressive kidney disorder caused by vascular damage to the glomerular capillaries, in patients with diabetes mellitus. "Complement C1s are associated with insulin resistance and diabetic retinopathy, whereas complement C7 has been associated with the early stages of diabetic kidney disease." (PMID 40333882, 2025).
Duchenne muscular dystrophy (1 paper, 2024). Duchenne muscular dystrophy (DMD) is a neuromuscular disease characterized by rapidly progressive muscle weakness and wasting due to degeneration of skeletal, smooth and cardiac muscle. "Most recently, both C1R and C1S subunits contribution to the development of Duchenne muscular dystrophy (DMD) by regulating innate immunity and inflammation has been studied." (PMID 39009419, 2024).
epilepsy (1 paper, 2016). A brain disorder characterized by episodes of abnormally increased neuronal discharge resulting in transient episodes of sensory or motor neurological dysfunction, or psychic dysfunction. "Taken together, we proposed that complement system might play key roles in the development of epilepsy by dysregulating the expression of C1QB, C1S and CFI." (PMID 26742644, 2016). "The dysregulation of C1QB, C1S, CFI, SCN3B and FN1 may be used potential gene targets for epilepsy treatment." (PMID 26742644, 2016). "Additionally, C1QB, C1S, CFI, SCN3B and FN1 may be potential therapeutic targets for epilepsy." (PMID 26742644, 2016).
Listeria infection (1 paper, 2021). "Eight of these genes were similarly inhibited by Listeria infection in PMH: they encode (i) the activating enzyme C1S of the C1 complex, (ii) the central component C3, (iii) the membrane-attack proteins C6 and C8A, and (iv) four complement regulators (C1QTNF6, CFH, CFHR2, VTN)." (PMID 34858876, 2021).
liver fibrosis (1 paper, 2022). "Along with the progression of liver fibrosis, IGHV, GAPDH, C1s, GRP78 and V-ATPase levels significantly increased, and PPBP, CD9, Lp(a) and SAP levels significantly decreased." (PMID 35797333, 2022).
malaria (1 paper, 2025). Malaria is a serious and sometimes fatal disease caused by a parasite that commonly infects a certain type of mosquito which feeds on humans. "The initially increased mRNA expression of C1ra, C1s, and C2 in the liver of vaccinated mice suggests that protective vaccination accelerates the complex malaria-induced initial activation patterns of CP and LP." (PMID 40243929, 2025).
metabolic syndrome (1 paper, 2013). A cluster of metabolic risk factors for CARDIOVASCULAR DISEASES and TYPE 2 DIABETES MELLITUS. "Interestingly, the expression of some of these genes (C1S, SAA2, ALCAM, CTSB, YKL-40 and tenomodulin) was found to be associated with some relevant metabolic syndrome features." (PMID 23975165, 2013).
muscular dystrophy (1 paper, 2011). Muscular dystrophy (MD) refers to a group of more than 30 genetic diseases characterized by progressive weakness and degeneration of the skeletal muscles that control movement. "C1S, C3 and C1QA genes, involved in complement mediated immunity contributing to muscular dystrophy, also showed heterogeneous expression across the dystrophy samples, with corresponding changes in tm-scores." (PMID 21453538, 2011).
pulmonary embolism (1 paper, 2023). The obstruction of the pulmonary artery or one of its branches by an embolus, sometimes associated with infarction of the lung. "This study aimed to investigate the potential application of plasma signal peptide‐complement C1r/C1s, Uegf and Bmp1‐epidermal growth factor domain‐containing protein 1 (SCUBE‐1) as a biomarker in the diagnosis of pulmonary embolism (PE)." (PMID 36748401, 2023).
sarcoma (1 paper, 2022). A usually aggressive malignant neoplasm of the soft tissue or bone. "The correlation between C1QBP and C1S was negative in TCGA-SARC, and their respective prognostic values in sarcoma were inverse." (PMID 35493104, 2022).
Turner syndrome (1 paper, 2022). Turner syndrome is a chromosomal disorder associated with the complete or partial absence of an X chromosome. "C1s protein is significantly enhanced in the plasma of women carrying Turner syndrome fetuses compared with pregnant women with normal fetuses in the second trimester of pregnancy." (PMID 35069847, 2022).
upper respiratory tract infections (1 paper, 2020). "We identified significant upregulation of several genes encoding components of the complement system, including C3, CFB, and C1S, uniquely within the CoV-2 dataset, in contrast to other upper respiratory tract infections (at 24 hpi)." (PMID 34786557, 2020).
urothelial carcinoma (1 paper, 2020). A malignant neoplasm derived from the transitional epithelium of the urinary tract (urinary bladder, ureter, urethra, or renal pelvis). "In urothelial carcinoma, the high expression of C1S correlated with adverse clinicopathological parameters." (PMID 32235718, 2020).